DDAH1 (dimethylarginine dimethylaminohydrolase 1)
Diseases named in the same sentence as DDAH1 in open-access papers (continued):
Sharing a sentence is not in itself a finding about the gene and the disease.
breast carcinoma (9 papers, 2017 to 2025). "Specifically, miR-193b-3p inhibits dimethylarginine dimethylaminohydrolase 1 (DDAH1), a regulator of angiogenesis and vasculogenic mimicry in aggressive breast cancer cells." (PMID 39567714, 2024). "Previous research comparing aggressive MDA-MB-231, MDA-MB-453, and BT549 breast cancer cell lines to normal mammary epithelial cells revealed over-expression of DDAH1." (PMID 39567714, 2024). "Small-molecule DDAH1 inhibitors significantly suppressed the formation of capillary-like tube structures by human breast cancer cells." (PMID 37627167, 2023). "The only study to specifically address regulation of DDAH1 in cancer was performed in breast cancer cell lines and identified the microRNA miR-193b as a direct negative regulator through the DDAH1 3′UTR." (PMID 31993367, 2019). "More recently, the potential therapeutic benefit of inhibiting DDAH1 was demonstrated for breast cancer." (PMID 31993367, 2019). "An upregulation of DDAH1 protein has also been observed in cohorts of melanoma and breast cancer cell lines, relative to normal melanocyte, and mammary epithelial cells, respectively." (PMID 31993367, 2019). "The extent to which DDAH1 can modulate breast cancer VM via ADMA-dependent or -independent processes is yet to be established." (PMID 31993367, 2019). "This is somewhat consistent with data in breast cancer cell lines, where a much greater change in DDAH1 expression was observed at the protein level compared to the transcript level." (PMID 31993367, 2019). "We have also recently published evidence for a novel role of DDAH1 in breast cancer, particularly in the more aggressive and invasive triple negative breast cancer (TNBC) molecular subtype." (PMID 31993367, 2019). "The present study identifies for the first time that DDAH1 is upregulated at both the mRNA and protein level in numerous breast cancer cell lines." (PMID 29070803, 2017). "To investigate the potential negative regulation of DDAH1 by miR-193b in breast cancer cells we transfected a miR-193b mimic into the MDA-MB-231 cell line." (PMID 29070803, 2017). "Inhibition of excessive DDAH1 expression and/or functional activity in breast cancer cells thus presents a means to indirectly inhibit NOS activity and reduce NO synthesis." (PMID 29070803, 2017). "We have shown that an inverse correlation between miR-193b and DDAH1 expression occurs in multiple breast cancer cell lines." (PMID 29070803, 2017). "Our data reveal a critical role for miR-193b in VM and demonstrates a mechanistic role for DDAH1 as a novel regulator of VM in breast cancer." (PMID 29070803, 2017). "Contrary results have been reported for prostate and breast cancers, in which DDAH1 was overexpressed in cell lines with aggressive phenotype and its knockout resulted in inhibition of cell migration, implicating the enzyme in breast and pancreatic cancer invasion and metastasis." (PMID 32932854, 2020). "Mir-193b has been previously reported as a tumor suppressor in breast cancer tissues and is frequently downregulated in other solid tumors such as melanoma, liver cancer, and prostate cancer, all of which are reported to exhibit increased DDAH1 expression." (PMID 31993367, 2019). "In alignment with findings in breast cancer cell lines, specific knockdown of DDAH1 protein in PC3 and LNCaP cell lines not only resulted in reduced L-citrulline formation, but also significantly increased intracellular ADMA concentration and decreased NO metabolite concentration." (PMID 31993367, 2019). "Whilst one of the roles of DDAH1 in tumor vessel development is likely facilitation of endothelial cell migration and invasion, as supported by DDAH1 overexpression conditioned media studies, initial reports in breast cancer cell lines suggest that DDAH1 is also a modulator of VM." (PMID 31993367, 2019).
breast carcinoma (continued). "We assessed the effect of DDAH1 inhibition in breast cancer cells across a variety of parameters: cell death, proliferation and migration, to determine whether they could contribute to the observed reduction in tube formation." (PMID 29070803, 2017). "We thus hypothesised that DDAH1 may play a regulatory role in breast cancer analogous to that reported in endothelial cells." (PMID 29070803, 2017). "We sought to quantify expression of DDAH1 and miR-193b in a selection of breast cancer cell lines." (PMID 29070803, 2017). "It is feasible to assume that miR-193b downregulation may enhance the expression of DDAH1 in breast cancer in vivo." (PMID 29070803, 2017). "Whilst our study provides data to better understand the mechanisms of VM formation in breast cancer, additional studies are warranted to further elucidate the role of DDAH1 in regards to tumour growth and progression, and to translate these findings to improved clinical outcomes." (PMID 29070803, 2017). "Due to an increase in DDAH1 expression among breast cancer cells representing the particularly invasive triple negative subtype, we hypothesised that DDAH1 regulates at least one aspect of breast cancer cell biology that contributes to tumour growth and/or metastasis." (PMID 29070803, 2017). "miR-193b regulates breast cancer cells (MDA-MB-231 cells) migration and VM formation via targeting dimethylarginine dimethylaminohydrolase 1 (DDAH1)." (PMID 32169087, 2020). "Taken together, these results demonstrate the functional importance of the miR-193b binding site within the DDAH1 3′UTR and provide evidence that DDAH1 is a direct target for miR-193b in breast cancer cells." (PMID 29070803, 2017). "Here, we identified over-expression of DDAH1 in aggressive MDA-MB-231, MDA-MB-453 and BT549 breast cancer cell lines when compared to normal mammary epithelial cells." (PMID 29070803, 2017). "In contrast, exogenous expression of DDAH1 in a DDAH1-null breast cancer cell line was not sufficient to induce VM, indicating that DDAH1 is required but not sufficient for VM in breast cancer." (PMID 31993367, 2019). "The functional significance of DDAH1 expression in breast cancer cells has not been previously documented." (PMID 29070803, 2017). "Due to the observed negative correlation between miR-193b and DDAH1 in breast cancer cell lines within this study, we hypothesised that DDAH1 is a target of miR-193b." (PMID 29070803, 2017). "Thus, we propose that DDAH1 is required, but not sufficient, for VM in breast cancer." (PMID 29070803, 2017).
gastric cancer (9 papers, 2017 to 2025). A primary or metastatic malignant neoplasm involving the stomach. "In contrast to these studies, DDAH1 protein downregulation was frequently detected in gastric cancer tissues, where its low expression was associated with more lymph node metastasis and poorer clinical outcome." (PMID 31993367, 2019). "Reduced levels of DDAH1 have been shown to mediate cell invasion and metastasis in gastric cancer through the WNT signaling pathway." (PMID 36983764, 2023). "A proneoplastic role has generally been attributed to DDAHs and the only evidence of DDAH1 acting as a tumor suppressor has been shown in gastric cancer." (PMID 34439753, 2021). "The DDAHs association with FGF2 warrants further investigation as well, as DDAH2 has recently been shown to alleviate fibrosis associated with diabetic cardiomyopathy and DDAH1 to inhibit the Wnt/β-catenin pathway, EMT, and gastric cancer cell migration." (PMID 32121248, 2020). "In alignment with this, downregulation of DDAH1 is reported in gastric cancer tissue and cell lines." (PMID 31993367, 2019). "Western blot analysis and qRT‐PCR also confirmed a lower expression of both DDAH1 protein and mRNA level in the gastric cancer tissues as compared to the adjacent normal tissues." (PMID 28580735, 2017). "Likewise, the dimethylarginine dimethylaminohydrolase 1 (DDAH1) gene, which plays an integral role in methylarginine removal, was found to be frequently upregulated in prostate cancer, downregulated in gastric cancer, and inhibited in attenuated triple negative breast cancer cells." (PMID 31892232, 2019). "Otherwise, low expression of Dimethylarginine dimethylaminohydrolase 1 (DDAH1), which exhibited tumor suppression effects on gastric cancer, was also recognized as a potential predictor for more aggressive phenotypes and poor prognosis of gastric cancer." (PMID 32310823, 2020). "It is possible that the tumor suppressor role of DDAH1 in gastric cancer is independent of its role in the ADMA/NO pathway." (PMID 31993367, 2019). "However, complicating DDAH1 relevance in cancer, the enzyme depletion and not its upregulation induced EMT in gastric cancer." (PMID 32932854, 2020).
prostate carcinoma (9 papers, 2011 to 2024). A carcinoma that arises from epithelial cells of the prostate gland. "Others have shown DDAH1 to promote the proliferation of prostate cancer cells via the ADMA/NO-dependent mechanism." (PMID 32121248, 2020). "In prostate cancer cell lines, exogenous expression of human DDAH1 increases cell proliferation, migration and invasion, and induces expression of multiple NO-regulated genes such as VEGF, HIF-1α, and iNOS." (PMID 31993367, 2019). "The release of pro-angiogenic signals bFGF and IL8 was also decreased following DDAH1 inhibition, and this translated into a decrease in endothelial cell tube formation when cells were cultured in conditioned media from the treated prostate cancer cells." (PMID 31993367, 2019). "In hormone-dependent (PC3) and hormone-independent (LNCaP) prostate cancer cell lines, both of which express DDAH1, generation of L-citrulline from the enzyme-substrate ADMA was observed in a colourimetric assay." (PMID 31993367, 2019). "In conclusion, the current study identified potential novel biomarkers for prostate cancer development and/or progression such as eIF4A3, DDAH1, ARG2, Prdx3, and Prdx4 from proteomic data using systems biology approach." (PMID 21347291, 2011). "Clouding matters, DDAH1 has promoted the migration of prostate cancer cells." (PMID 32121248, 2020). "Intriguingly, DDAH1 autoantibodies have been detected in sera of prostate cancer patients and proposed as a new marker for a novel prostate cancer and benign hyperplasia diagnostic, improving on the traditional prostate specific antigen (PSA) test which often yields false-positive results." (PMID 31993367, 2019). "Furthermore, overexpression of an active site mutant human DDAH1 does not significantly alter cell behavior or VEGF expression, providing additional evidence that hydrolytic activity of DDAH1 is required for mediation of prostate cancer growth." (PMID 31993367, 2019). "In addition, proteomic analysis of prostate biopsies to distinguish hyperplasia and cancer also found upregulation of DDAH1 in prostate cancer." (PMID 26218761, 2015). "In addition, 14-3-3 sigma, GLRX3 and DDAH1 have been shown to function in various kinds of tumors as well as prostate cancer." (PMID 26218761, 2015). "Protein network analysis and clustering of differentially expressed proteins revealed new targets such as DDAH1, ARG2, EIF4A3, Par4, PPA2, Prdx3 and Prdx4, which need further validation to define their potential application in clinical relevance in prostate cancer." (PMID 21347291, 2011). "Additionally, modulation of the angiogenic pathway was observed in prostate cancer cells following treatment with DD1E5: the pro-angiogenic factors VEGF, iNOS, c-Myc, and HIF-1α were all downregulated, indicating that DDAH1 inhibition attenuates the angiogenic potential of DDAH1+ cells." (PMID 31993367, 2019). "DDAH1 is frequently upregulated in prostate cancer, where it promotes tumor growth and angiogenesis, suggesting that anti-cancer drugs that induce ADMA or that inhibit DDAH1 could potentially be useful in treating tumors that are influenced by the pro-tumorigenic properties of NO." (PMID 30082427, 2018).
atherosclerosis (7 papers, 2014 to 2024). A disease characterized by the build-up of fatty material and calcium deposition in the arterial wall resulting in partial or complete occlusion of the arterial lumen. "In a mouse model of atherosclerosis (ApoE-deficient mice), DDAH1 overexpression ameliorated atherosclerotic lesion formation and vascular endothelial function within the aorta." (PMID 24690995, 2014). "The purpose of the work was to study the impact of the endogenous nitric oxide synthase (NOS) inhibitor asymmetric dimethylarginine (ADMA) and its degrading enzyme, dimethylarginine dimethylaminohydrolase (DDAH1), on atherosclerosis in subtotally nephrectomized (SNX) ApoE-deficient mice." (PMID 24690995, 2014). "In summary, our findings demonstrate that DMY reduces lipid burden and inhibits atherosclerosis, at least in part, by decreasing miR‐21 expression and in turn activating DDAH1‐medaited ADMA‐eNOS‐NO pathway in ECs." (PMID 32301289, 2020). "Notably, ASS1 and DDAH1 also contribute to the regulation of vascular NO production to prevent inflammatory processes such as atherosclerosis." (PMID 38894980, 2024). "Furthermore, miR-21- facilitates the pathogenesis of atherosclerosis by regulating DDAH1-ADMA-eNOS-NO pathway." (PMID 36561848, 2022). "Thus, targeting DDAH1‐ADMA–mediated eNOS‐NO activation and associated endothelial function holds great potential for developing novel therapeutic approaches for atherosclerosis." (PMID 32301289, 2020). "In the present study, we assessed the impact of CKD on the ADMA/DDAH axis in atherosclerosis by studying atherosclerotic lesion formation in subtotally nephrectomized (SNX) ApoE-deficient mice with or without overexpression of DDAH1." (PMID 24690995, 2014). "Overexpression of the ADMA degrading enzyme, DDAH1, did not ameliorate atherosclerosis in ApoE-deficient SNX mice." (PMID 24690995, 2014). "Thus, we hypothesized that miR‐21 abrogates the protective effects of DMY on atherosclerosis by decreasing DDAH1 expression." (PMID 32301289, 2020). "Furthermore, the degree of atherosclerosis in ApoE-deficient mice with SNX was similar in mice with or without overexpression of DDAH1." (PMID 24690995, 2014). "Recently, the DDAH1‐ADMA‐eNOS pathway has emerged as an important regulator in mediating NO production and atherosclerosis." (PMID 32301289, 2020). "Taken together, these data demonstrate that de‐repression of DDAH1‐ADMA‐eNOS‐NO pathway due to the reduction of miR‐21 plays a critical role in the protective effects of DMY on endothelial function and atherosclerosis." (PMID 32301289, 2020). "In addition, overexpression of the ADMA degrading enzyme, DDAH1, in SNX treated ApoE-deficient mice does not ameliorate atherosclerosis." (PMID 24690995, 2014).
triple-negative breast carcinoma (7 papers, 2018 to 2025). An invasive breast carcinoma which is negative for expression of estrogen receptor (ER), progesterone receptor (PR), and human epidermal growth factor receptor 2 (HER2). "ZST316 and ZST152 have been shown in vitro to suppress vasculogenic mimicry, an alternative neo-vascularization pathway driven by iNOS and DDAH1 that increases metastatic potential and adverse outcomes, in triple-negative breast cancer cells." (PMID 35164277, 2022). "Although, these results are somewhat preliminary and need further confirmation with in vivo studies, they suggest a promising role for DDAH1 inhibition as a novel treatment strategy in triple negative breast cancer." (PMID 31993367, 2019). "In addition, previous data showed that DDAH1 is overexpressed in some triple-negative breast cancer cell lines, contributing to their aggressiveness." (PMID 40140975, 2025). "In particular, the recent demonstration by our group that DDAH1 inhibition with ZST316 suppresses in vitro vasculogenic mimicry and migration of MDA-MD-231 cells, an established triple-negative breast cancer cell line, warrants the investigation of these effects in xenograft studies." (PMID 35164277, 2022). "In our own studies assessing VM in triple negative breast cancer cell lines, specific knockdown of endogenous DDAH1 significantly attenuated cell migration, but not proliferation." (PMID 31993367, 2019).
type 2 diabetes (6 papers, 2010 to 2022). "The rs1241321 A/G single nucleotide polymorphism in the dimethylarginine dimethylaminohydrolase 1 (DDAH1) gene is associated with an increased risk of major adverse cardiac events in 309 Taiwanese subjects with type 2 diabetes and CAD." (PMID 22533709, 2012). "In this study, SNP rs1241321 in DDAH1 was found to be associated with a higher risk of type 2 diabetes independently of the plasma ADMA level." (PMID 21303562, 2011). "In summary, these findings suggest that the interactions among plasma ADMA level, DDAH1 polymorphism, and type 2 diabetes are much more complex than previously thought and are far from being completely understood." (PMID 21303562, 2011). "For example, SNP (single nucleotide polymorphism) rs1241321 in DDAH1 was found to be associated with a higher type 2 diabetes risk independently of plasma ADMA levels." (PMID 21781316, 2011). "From July 2006 to June 2009, we assessed the association between polymorphisms in DDAH1 and type 2 diabetes in 814 consecutive unrelated subjects, including 309 type 2 diabetic patients and 505 non-diabetic individuals." (PMID 21303562, 2011). "Our study provides the first evidence that SNP rs1241321 in DDAH1 is associated with insulin sensitivity, type 2 diabetes and their long-term prognosis, independently of plasma ADMA levels." (PMID 21303562, 2011). "In this prospective study, we assessed the association between single nucleotide polymorphisms (SNPs) in DDAH1 and type 2 diabetes and their long-term outcome in a population undergoing diagnostic coronary angiography." (PMID 21303562, 2011). "Our results provide the first evidence that SNP rs1241321 in DDAH1 is associated with type 2 diabetes and its long-term outcome." (PMID 21303562, 2011). "DDAH-1 expression was reduced during diabetogenesis in the liver, kidney and adipose tissue of mice with a point mutation in leptin receptor, an experimental motel of type 2 diabetes." (PMID 23578341, 2013). "We first assessed the association of each DDAH1 SNP with type 2 diabetes." (PMID 21303562, 2011). "We sought to determine whether serum ADMA levels in type 2 diabetes are influenced by common polymorphisms in the DDAH1 and DDAH2 genes." (PMID 20209122, 2010). "This study found genetic variation in the DDAH1 and DDAH2 genes to be significantly associated with serum ADMA levels in participants with type 2 diabetes." (PMID 20209122, 2010). "Dimethylarginine dimethylaminohydrolase 1 (DDAH1) is the major enzyme eliminating ADMA in humans, but the effect of genetic variations in DDAH1 on type 2 diabetes and its long-term outcome are unknown." (PMID 21303562, 2011). "The DDAH1 gene may play a potential role in the pathogenesis of type 2 diabetes." (PMID 21303562, 2011). "Thus, the DDAH1 gene could play an important role in the pathogenesis of type 2 diabetes." (PMID 21781316, 2011). "In conclusion, genetic variation in DDAH1 and DDAH2 genes was found to be strongly and significantly associated with serum ADMA levels in patients with type 2 diabetes, especially in those without retinopathy." (PMID 20209122, 2010). "However, the effect of genetic variations of DDAH1 on type 2 diabetes has not been reported." (PMID 21303562, 2011).